PPARG (peroxisome proliferator activated receptor gamma)
Diseases named in the same sentence as PPARG in open-access papers (continued):
Sharing a sentence is not in itself a finding about the gene and the disease.
tumor (continued). "PPARγ and PPARα ligands have been shown to promote the differentiation of various tumor cell lines, including breast, lung, prostate, leukemia, colon, melanoma, and liver cancers." (PMID 29565812, 2018). "The overexpression of PPARγ suppresses cell survival by inhibiting cell proliferation and tumor growth." (PMID 30323259, 2018). "We further confirm, through interrogation of multiple engineered lines and clinical data sets, that tumor-intrinsic PPARγ/RXRα pathway activity inhibits host immune response through suppressing expression and secretion of inflammatory factors." (PMID 28740126, 2017). "More recently, PPARγ's role in cancer has become apparent; PPARγ hinders tumor development and progression, in most cases by modulating differentiation, proliferation, apoptosis, and motility of cancer cells through a variety of molecular pathways." (PMID 28316613, 2017). "Specifically, in these animals, C/EBPα and PPARγ expression were 26-times (p<0.001) and 59-times (p<0.001) higher, respectively, in the tumor-bearing state compared with reference animals." (PMID 28832677, 2017). "This clearly demonstrates that epidermal PPARγ plays an important indirect role in B16F10 tumor growth." (PMID 29228682, 2017). "The evidence: The role of PPARγ in lineage specification is often thought of in the context of its ability to regulate several tumor suppressor genes." (PMID 28881566, 2017). "Peroxisome-proliferator-activated receptors (PPARs) are nuclear hormone receptors including PPARα, PPARδ and PPARγ, which play an important role in regulating cancer cell proliferation, survival, apoptosis, and tumor growth." (PMID 28948004, 2017). "Taken together, these results indicate that PPARG inhibition is highly effective in abrogating the tumor‐initiation capacity of AML tumors." (PMID 28275008, 2017). "Sumoylation of PPARγ has been previously reported in regulation of PPARγ transcriptional activity for anti-inflammation as well as tumor suppression." (PMID 29137280, 2017). "Expression of C/EBPα and PPARγ showed remarkable increases in response to the tumor-bearing state and subsequent chemotherapy treatment in rats on the control diet." (PMID 28832677, 2017). "More recently, however, PPARG antagonism was successfully used to halt the in vitro growth of tumor cells of various sources [e.g., breast, esophagus, and pancreas]." (PMID 28275008, 2017). "Some studies show that PAX8/PPARγ has a dominant negative effect on wild type PPARγ, which is believed to act as a tumor suppressor." (PMID 28117295, 2017). "To confirm the role of caspase-1 in promoting tumor growth, we analyzed caspase-1 and truncated PPARγ fragment in TAMs in each group, which validate the phenotype of BMDMs in this experiments." (PMID 28974683, 2017). "Our results demonstrated that PPARγ activation by troglitazone enhances TRAIL-mediated tumor cell death in A549 cells via regulation of autophagy flux." (PMID 28460464, 2017). "Even though the PPARs family contains PPARα, PPARγ and PPARδ, they serve as different functions in tumor development." (PMID 28948004, 2017). "Increasing evidences show that PPARα or PPARγ inhibits tumor progression, which acts as tumor suppressors, while some reports show that PPARα is associated with tumor progression." (PMID 28948004, 2017). "In conclusion, our current data indicates that epidermal PPARγ plays a robust role in modulating cutaneous inflammation, cutaneous immune responses and potentially anti-tumor immune surveillance." (PMID 29228682, 2017). "Peroxisome proliferator-activated receptor gamma (PPARγ) is a nuclear hormone receptor regulating transcription of diverse gene sets involved in inflammation, metabolism, and suppressing tumor growth." (PMID 29137280, 2017). "We next examined the effect of PPARG inhibition on Xn cells, representing an enriched population of tumor‐propagating cells." (PMID 28275008, 2017).
tumor (continued). "Activated PPARγ is also antitumorigenic and antimetastatic, regulating several functions of cancer cells and controlling the tumor microenvironment." (PMID 28316613, 2017). "First, PPARγ inhibition should enhance the appearance of the ER+ tumor lineage, enabling sensitivity to anti-ER therapy." (PMID 28881566, 2017). "In summary, PPARγ activation by troglitazone sensitizes TRAIL-induced tumor cell death in A549 cells via autophagy flux." (PMID 28460464, 2017). "ARNT2 and PPARG showed positive correlations with the tumor grade of ESCC and were up‐regulated in G3 (poorly‐differentiated) compared to G1 (well‐differentiated)." (PMID 28904855, 2017). "Together, these studies suggest that one change that accompanies tumor progression to castration-resistance is an increase in the amount of functional PPARγ." (PMID 29181019, 2017). "Consistent with this, overexpression of PPARγ inhibits cell proliferation and tumor growth, but this is reversed in PPARγ silenced cancer cells or activated EGFR signaling." (PMID 28948004, 2017). "C/EBPα and PPARγ expression further significantly increased after cycle-2 compared with tumor-bearing (p<0.001 and p<0.001, respectively) and cycle-1 animals (p<0.001 and p<0.001, respectively) on the control diet." (PMID 28832677, 2017). "The up-regulation of TXNIP expression and subsequent induction of apoptosis have also been shown to be the mechanism of the anti-tumor effect by various agents such as anisomycin, oxidative stress, dexamethasone, PPARγ, calcium influx and potassium ion." (PMID 28029659, 2017). "Analysis of gene expression changes along Xn propagation in vivo and in comparison with normal human kidney, uncovered PPARG as a regulator of tumor growth." (PMID 28275008, 2017). "Peroxisome proliferator-activated receptor gamma (PPARγ) is another tumor suppressor in colorectal carcinogenesis." (PMID 27926503, 2017). "In contrast, in cancer, increasing evidence indicates a beneficial tumor suppressive role for PPARγ (e.g., gastric, pancreatic, and hepatic cancers)." (PMID 28167956, 2017). "Second, detailed bioinformatic analysis showed that various genes regulating tumor growth, non‐adipogenic differentiation, and the mTOR pathway are regulated by PPARG." (PMID 28275008, 2017). "Among the ligands, we identified betulinic acid (BA), a compound already known for its anti-inflammatory, anti-tumour and antidiabetic properties, as a PPARγ and PPARα antagonist." (PMID 28720829, 2017). "Taken together, these results indicate that PPARγ inactivation in Ly6G+ cells facilitated their transendothelial migration, and stimulation of tumor cell proliferation and migration." (PMID 26625314, 2016). "Although PPARγ expression was significantly expressed in the tumor, adipocytic development was inhibited." (PMID 27401457, 2016). "Here we have uncovered a crucial yet previously unrecognized role of macrophage PPARγ in suppressing cancer progression and mediating the anti-tumor effects of rosiglitazone." (PMID 27692066, 2016). "The authors identify the tumor promoting role of PPARγ in the metabolic symbiosis between stoma and epithelial cancer cells, where cancer associated fibroblasts provided intermediates for mitochondrial metabolism to cancer cells." (PMID 28115925, 2016). "Multiple studies have suggested a role for LXR and PPARG metabolic nuclear receptors in tumor cell biology." (PMID 27401066, 2016). "Higher levels of PPARG promoter methylation were found in advanced tumour stages while earlier stages showed lower methylation levels." (PMID 27579030, 2016). "The PAX8/PPARγ gene also occurs in FTA; PAX8/PPARγ exerts a dominant-negative effect on the wild-type tumor suppressor PPARγ and also trans-activates PAX8-responsive genes." (PMID 26886957, 2016). "These pharmacological findings support that the PPARγ repression of Gpr132 in macrophages is a significant contributor to the anti-tumor effects of rosiglitazone." (PMID 27692066, 2016).
tumor (continued). "In another study, CBD exhibited anti-tumor effects that were reversed by co-administration of a PPARγ antagonist in vivo." (PMID 27774065, 2016). "PPARγ is reported to possess an antitumor activity through the suppression of tumor proliferation and invasion and the induction of differentiation and apoptosis in cancer cells." (PMID 27401457, 2016). "In fact, some research has supported the idea that PPARγ can act as a tumour suppressor or tumour promoter, depending on the tumour type and development stage." (PMID 27769068, 2016). "Overexpression of pro-inflammatory molecules (e.g., apoptosis inhibitor 6 and matrix metalloproteinase 12) that are negatively regulated by PPARγ has been reported to induce chronic inflammation and spontaneous tumor formation." (PMID 26625314, 2016). "Again, a word of caution must be said due to the seemingly tumour-promoting effects of PPARG found sporadically." (PMID 27579030, 2016). "In vitro experiments showed that PPARγ suppresses tumor progression, namely, growth, migration, and angiogenesis in HCC cells." (PMID 27483249, 2016). "As the master regulator of adipogenic differentiation, PPARγ has been described to promote differentiation programs in a variety of tumor cell types, inducing cell-cycle arrest, apoptosis/anoikis, and inhibiting EMT, angiogenesis, and metastasis." (PMID 28115925, 2016). "According to the quantification of western blot bands, the level of PPARγ phosphorylation in the liver in tumour mice was 2.9 times higher than that in normal mice." (PMID 27769068, 2016). "The paradoxical effects resulting from PPARγ activation are derived from a complex balance of the anti- versus pro-tumour functions of the PPARγ protein and its ligands in a given system." (PMID 27769068, 2016). "In nude mouse assay, suppression of PPARγ in PC3-M cells significantly reduced the size of tumours by 99%, tumour incidence by 90%." (PMID 26814431, 2016). "Our analysis revealed that a significantly positive correlation exists between PPARγ and KLF4 expression in HCC tissues, suggesting that PPARγ collaborates with KLF4 to facilitate tumor suppression." (PMID 27483249, 2016). "Sixteen pairs of liver samples from normal (N) mice or tumour-bearing (T) mice were collected to detect the phosphorylated and total PPARγ by western blot." (PMID 27769068, 2016). "Our in vivo and in vitro findings all support an anti-inflammatory and anti-tumor role of macrophage PPARγ activation, and a pro-inflammatory and pro-tumor effect of macrophage PPARγ deletion." (PMID 27692066, 2016). "This can be envisioned to result in part from competition between the tumor promoting effects of PPARδ and the tumor suppressor effects of PPARγ." (PMID 28077942, 2016). "Together, these findings indicate that activation of macrophage PPARγ by either endogenous or synthetic agonists suppresses tumor growth." (PMID 27692066, 2016). "We demonstrated that HCC patients with low PPARγ expression were significantly younger than 65 years old and exhibited more tumor numbers, more MVI, and more advanced TNM stages at diagnosis than HCC patients with high PPARγ expression." (PMID 27483249, 2016). "Lipids also function as PPARγ agonists, and the PPARγ pathway has evident tumor-promoting properties in multiple cancers, as recently reviewed in Ref." (PMID 27379019, 2016). "Angiogenesis and secretion of certain matrix metalloproteinases and extracellular matrix proteins within the tumor microenvironment are also regulated by PPARγ." (PMID 27698657, 2016). "It has been shown, both in vitro and in vitro, that the tumours are capable of epigenetically silencing both the vitamin D and the PPARG system." (PMID 27579030, 2016). "Taken together, these results suggest that activation of the PPARγ pathway in lal−/− Ly6G+ cells impaired the capacity of these myeloid cells to stimulate tumor cell proliferation." (PMID 26625314, 2016).
tumor (continued). "Together, this work highlights a novel connection between PPARγ agonist in inducing adipogenesis and mimicking the tumor suppressive hippo pathway." (PMID 27528232, 2016). "Various clinicopathological parameters, including patient age (p = 0.006), tumor number (p = 0.038), MVI (p = 0.008), and TNM stage (p = 0.013), exhibited significant associations with PPARγ expression." (PMID 27483249, 2016). "Nuclear expression of PPARγ in the only tumour produced by PC3-M-PPARγ-si-H cells was weakly positive." (PMID 26814431, 2016). "After that, we also compared PPARγ phosphorylation in Ser273 between the normal and tumour tissue from the mice liver and between phase II and III tumour from human liver." (PMID 27769068, 2016). "Genetic Gpr132 deletion not only retards inflammation and cancer growth but also abrogates the anti-tumor effects of PPARγ and rosiglitazone." (PMID 27692066, 2016). "Among the many downstream events that mediate the pro-tumor effects of inflammatory macrophages, it is possible that macrophage PPARγ not only regulates cancer cell behavior but also modulates tumor-infiltrating lymphocytes (TILs) to alter immune surveillance." (PMID 27692066, 2016). "Together, these findings suggest that macrophage PPARγ deletion changes both the number and property of TAMs to establish a pro-inflammatory tumor environment." (PMID 27692066, 2016). "On the other hand, DMBA + ROSI-treated PPARγ-MG KO tumours showed a dramatic increase in Cox-2 protein levels suggesting that a PPARγ-independent process is likely responsible." (PMID 25889730, 2015). "Higher mRNA or protein expression in well-differentiated tumors compared to poorly differentiated tumors and tumors with poor prognosis is interpreted as protective effect of PPARγ in tumor development." (PMID 25866814, 2015). "The anti-tumor activity of PPARγ agonists on tumor cell lines and animal models have been well described." (PMID 26091518, 2015). "Further, the genes related to AT development (PPARγ and CEBPα) were down-regulated on day 4 after tumor cell inoculation (very early stage)." (PMID 25807446, 2015). "Etodolac negatively regulates PPARγ function which then downregulates cyclin D1 leading to tumor growth inhibition." (PMID 26275572, 2015). "In other tumor models, ibuprofen was shown to bind and activate the peroxisome proliferator-activated receptor γ (PPARγ) as observed from reporter gene assays." (PMID 26485029, 2015). "Some of these switches occur in known tumor drivers, including PPARG, CCND3, RALGDS, MITF, PRDM1, ABI1 and MYH11, for which the switch implies a change in the protein product." (PMID 25578962, 2015). "Identification of the contribution of PPARγ to tumor development and progression is further complicated by crosstalk with other pathways." (PMID 25866814, 2015). "The description of all mechanisms of TZDs is beyond the scope of this review but one important signaling pathway for tumor cells and for surrounding tissue (tumor microenvironment) each illustrates the variety of PPARγ effects." (PMID 25866814, 2015). "Myeloid-specific expression of human LAL (hLAL) to restore the PPARγ function in lal−/− mice reverses both immunosuppression and tumor stimulation." (PMID 26501068, 2015). "In subjects exposed to etodolac with pre- and postexposure flash frozen tumor available (n = 15), we evaluated the gene expression levels associated with the COX-2 pathway (COX-2 and β-catenin) and the RXRα pathway (RXRα, PPARγ, and cyclin D1)." (PMID 26275572, 2015). "ROSI cotreatment repressed Cox-2 in PPARγ-WT tumours, but dramatically amplified it in PPARγ-MG KOs." (PMID 25889730, 2015). "In the DMBA Only-treated group, PPARγ-WT mice had a total tumour incidence of 80 ± 8% compared to 67 ± 8% for PPARγ-MG KOs." (PMID 25889730, 2015). "In the DMBA + ROSI group, total tumour incidence was similar for PPARγ-WTs (76 ± 7%) and PPARγ-MG KO (76 ± 10%) mice." (PMID 25889730, 2015).
tumor (continued). "The anti-tumor activity of Peroxisome Proliferator-Activated Receptor gamma (PPARγ) agonists has been reported in 1997." (PMID 26091518, 2015). "Tumours taken from PPARγ-WT mice treated with DMBA Only were primarily classified as malignant carcinomas with mixed squamous differentiation." (PMID 25889730, 2015). "Studies linking tumor prognosis and PPARγ expression were mainly based on immunohistochemical detection of the PPARγ antigen in paraffin-embedded tissue." (PMID 25866814, 2015). "In fully tumorigenic HBECs with inducible expression of PPARγ, TZD treatments inhibited tumor cell growth, clonogenecity, and cell migration in a PPARγ-sumoylation dependent manner." (PMID 26244663, 2015). "Mechanistically, the tumor-promoting effect of G9a appears to bypass its known downstream signaling molecules such as EpCAM, PPARγ, and Wnt." (PMID 25595900, 2015). "We provided the first direct in vivo evidence that PPARγ normally stops the growth and spread of breast and other tumour progression in a 7,12-dimethylbenz[a] anthracene (DMBA)-treated haploinsufficient PPARγ(+/-) mouse model." (PMID 25889730, 2015). "TXNIP is highly upregulated when PPARγ, which we have previously shown to be a tumor promoter, is depleted from ATC cells." (PMID 24645981, 2014). "In a US Phase 1 study, archived tumor specimens of patients with SD or PR showed significantly higher PPARγ and RXR expression than those with PD." (PMID 24337768, 2014). "Many studies have provided evidence that DHA inhibits the tumor development through activation of PPARγ (e.g. the growth of human lung cancer cells)." (PMID 24524207, 2014). "PPARγ agonists such as troglitazone, rosiglitazone, and pioglitazone have been tested in vitro and exhibited growth inhibitions as well as apoptosis of tumor cells." (PMID 25276134, 2014). "PPARγ inhibits cell proliferation and tumor angiogenesis, induces apoptosis and reduces invasiveness following activation by specific ligands, such as the prostaglandin D2 metabolite, 15-d-PGJ2 and rosiglitazone (Ros)." (PMID 24944709, 2014). "Apart from these positive effects, activation of PPARγ by glitazones attenuates systemic inflammation and reduces tumor growth and angiogenesis." (PMID 24524207, 2014). "Specifically, PPARγ activation was effective in arresting the proliferation of dedifferentiated tumor cells." (PMID 24603556, 2014). "No clear relationship was detected between treatment efficacies and plasma levels of adiponectin as well as the expression levels of PPARγ and the retinoid X receptor in tumor tissues." (PMID 24337768, 2014). "PPARγ expression has been described in a range of other neoplasias including colon, lung, prostate, bladder, breast, duodenal, and thyroid." (PMID 24672773, 2014). "Activation of PPARγ by natural ligands such as PUFAs (mainly docosahexaenoic acid and eicosapentaenoic acid) results in a functional response in the tumor cells." (PMID 24524207, 2014). "Activation of PPARγ during tumour progression is deleterious as it also has an important role in the modulation of tumour microenvironment by altering the immune status in epithelial cancers." (PMID 24999478, 2014). "This fusion has been found to accelerate cell growth, inhibiting normal tumor suppression by PPARγ and therefore acts as an oncogene." (PMID 25276134, 2014). "In the present study, exposure of tumor cells to adipocyte-derived factors led to PPARγ-driven FABP4 upregulation followed by PPARγ downregulation." (PMID 24240026, 2013). "In the present work we demonstrated that, through activation of PPARγ, long-term I2 treatment increases the tumor sensitivity to DOX, inhibits chemoresistance, and exerts cardioprotective effects, allowing a four-fold reduction in the therapeutic dose of DOX." (PMID 23705792, 2013).